STAC2 (SH3 and cysteine rich domain 2)
Description:
Plays a redundant role in promoting the expression of calcium channel CACNA1S at the cell membrane, and thereby contributes to increased channel activity. Slows down the inactivation rate of the calcium channel CACNA1C. Negative regulator of osteoclastogenesis. Following TNFSF11/RANKL stimulation, interacts with TNFRSF11A/RANK and interferes with the formation of the TNFRSF11A signaling complex, leading to the suppression of TNFSF11-initiated NF-kappa-B and MAPK signaling pathways. Impairs TNFSF11-induced, BTK/TEC-catalyzed PLCG2 phosphorylation and activation (By similarity).
Synonyms: 24b2; 24b2/STAC2
Tractability: Antibody: UniProt places it where antibodies can reach, with medium confidence; its Gene Ontology location is reachable by antibodies, with medium confidence.
Gene: Protein-coding gene on chromosome 17 (39,210,540 to 39,225,945, reverse strand). Ensembl gene ENSG00000141750.
Subcellular location: Cytoplasm, cytosol; Cell membrane; Cell membrane, sarcolemma; Membrane raft
Subcellular location (Human Protein Atlas): Cytosol
Gene Ontology:
Molecular function: protein binding; calcium channel regulator activity
Biological process: negative regulation of osteoclast differentiation; positive regulation of protein localization to plasma membrane; positive regulation of voltage-gated calcium channel activity; skeletal muscle contraction
Cellular component: cytoplasmic side of plasma membrane; membrane raft; plasma membrane; cytosol; sarcolemma
Genetic constraint (gnomAD): Loss-of-function variants: 36 observed, 48.09 expected, observed/expected ratio (o/e) 0.75, 90% interval 0.57 to 0.99. The upper end of that interval is the gene's LOEUF score, 0.99, which puts it in group 4 of 6, group 1 being the genes least tolerant of losing a copy. Missense variants: 527 observed, 546.76 expected, observed/expected ratio (o/e) 0.96, 90% interval 0.9 to 1.04. Synonymous variants: 239 observed, 217.76 expected, observed/expected ratio (o/e) 1.1, 90% interval 0.99 to 1.22.
Homologues: Orthologues: chimpanzee STAC2 (99% identical), macaque STAC2 (98% identical), mouse Stac2 (93% identical), rat Stac2 (93% identical), dog STAC2 (92% identical), rabbit STAC2 (87% identical), pig STAC2 (86% identical), guinea pig STAC2 (82% identical), tropical clawed frog stac2 (63% identical). Paralogues in human: STAC (45% identical), STAC3 (33% identical).
Diseases named in the same sentence as STAC2 in open-access papers:
STAC2 is named in the same sentence as 8 diseases in open-access papers, as found by Europe PMC text mining. Sharing a sentence is not in itself a finding about the gene and the disease. The quoted sentences say what the papers report.
breast carcinoma (5 papers, 2016 to 2025). "STAC2 has been previously identified as a potential tumor suppressor gene in various cancers, including colorectal, and breast cancer." (PMID 41562091, 2025). "Thus, FREM1 may play the similar roles and prognostic values, whereas STAC2 may play different roles and prognostic values in breast cancer and LumB-subtype breast cancer." (PMID 33644115, 2021). "In the selected key specific DEGs for LumB-subtype breast cancer, the expression of CNTD2, NEURL, STAC2, AKR1C2, IL6, FREM1, and HOXA4 were significantly correlated with the prognostic survival of the patients." (PMID 33644115, 2021). "Our results showed that STAC2 and FREM1 were specifically downregulated and their low expressions predicted low RFS and OS (p < 0.05) in LumB-subtype breast cancer." (PMID 33644115, 2021). "Further studies are needed to determine the exact roles prognostic values of STAC2 and FREM1 in breast cancer and LumB-subtype breast cancer." (PMID 33644115, 2021). "CNTD2, NEURL, STAC2, IL6, FREM1, and HOXA4 may be involved in recurrence of LumB-subtype breast cancer." (PMID 33644115, 2021). "In general, the analytical data suggest that STAC2, FREM1, and AKR1C2 may be involved in the tumorigenesis to improve OS of patients with LumB-subtype breast cancer." (PMID 33644115, 2021). "Moreover, STAC2, AKR1C2, and HOXA4 can be used as the specific prognostic markers for LumB-subtype breast cancer." (PMID 33644115, 2021). "Finally, 6 upregulated DEGs (CST2, DRP2, CLEC5A, SCD, KIAA1211, DTL) and 6 downregulated DEGs (STAC2, BTNL9, CA4, CD300LG, GPIHBP1 and PIGR), were confirmed in a quantitative real time PCR comparison of breast cancer and paracancerous breast tissues from 8 clinical specimens." (PMID 31182966, 2019).
colorectal cancer (1 paper, 2020). A primary or metastatic malignant neoplasm that affects the colon or rectum. "Here we demonstrated that CGI hypermethylation of FIGN, HTRA3, BDNF, HCN4 and STAC2 in colorectal cancer is associated with patient progression to metastasis, identifying them as putative future biomarkers for CRC progression." (PMID 32971738, 2020). "Statistical association between poor survival and hypermethylation of CGI was established in FIGN (p = 0.030), HTRA3 (p = 0.009), BDNF (p = 0.002), HCN4 (p = 0.018) and STAC2 (p = 0.007) and may be used as potential markers for metastasis progression in colorectal cancer." (PMID 32971738, 2020). "In addition, the hypermethylation of FIGN, HTRA3, BDNF, HCN4 and STAC2 could be utilised in primary tumour as biomarkers of colorectal cancer prognosis." (PMID 32971738, 2020).
leukoplakia (1 paper, 2025). A white patch or plaque on a mucous membrane that cannot be characterized clinically or pathologically as any other disease. "Although our analysis compared OSCC to BC samples, 19 significant genes overlapped with Farah and Fox’s 47 differentially expressed genes (DEGs), including the upregulation of ODC1 and LCN2 and the downregulation of COL1A1, COL11A1, and STAC2 in dysplastic leukoplakia samples." (PMID 40650045, 2025).
cancer (5 papers, 2017 to 2025). A tumor composed of atypical neoplastic, often pleomorphic cells that invade other tissues. "Our results demonstrated that the expression of STAC2 was significantly decreased in PCa tissues compared to adjacent normal tissues, which is consistent with previous studies on other types of cancers." (PMID 41562091, 2025). "STAC2 may be an interesting biomarker, as it has a known biological function in cancer progression." (PMID 32971738, 2020). "HCN4 and STAC2 have otherwise not been reported in cancer research so far, especially not regarding their methylation status." (PMID 32971738, 2020). "Of the 201 downregulated genes, 125 were identified in the previous study (GEO results) and only 76, such as cysteine rich domain 2 (STAC2), BTNL9, CA4, GPIHBP1 and PIGR, had not been studied on any cancer." (PMID 31182966, 2019).
tumor (2 papers, 2020 to 2025). "Additionally, we observed an association between low STAC2 expression and higher tumor grade and advanced clinical stage, suggesting that STAC2 may serve as a prognostic marker for PCa." (PMID 41562091, 2025). "Two of these genes, HTRA3 and STAC2, were found as the top five hypermethylated CGIs in primary tumour and LNM, respectively." (PMID 32971738, 2020).
respiratory diseases (1 paper, 2020). "The top ten genes (Clca1, Chil4, Itln1, Tff1, Muc5ac, Clca3b, Chodl, Pla2g4c, Mmp10, and Stac2) with the highest fold change are involved in various inflammatory responses and respiratory diseases." (PMID 33066398, 2020).
STAC2 also shares sentences with these, for which no sentence is quoted: heart failure (1 paper); infection (1).